MAD2L2 (mitotic arrest deficient 2 like 2)
Description:
Adapter protein able to interact with different proteins and involved in different biological processes. Mediates the interaction between the error-prone DNA polymerase zeta catalytic subunit REV3L and the inserter polymerase REV1, thereby mediating the second polymerase switching in translesion DNA synthesis. Translesion DNA synthesis releases the replication blockade of replicative polymerases, stalled in presence of DNA lesions. Component of the shieldin complex, which plays an important role in repair of DNA double-stranded breaks (DSBs). During G1 and S phase of the cell cycle, the complex functions downstream of TP53BP1 to promote non-homologous end joining (NHEJ) and suppress DNA end resection. Mediates various NHEJ-dependent processes including immunoglobulin class-switch recombination, and fusion of unprotected telomeres. May also regulate another aspect of cellular response to DNA damage through regulation of the JNK-mediated phosphorylation and activation of the transcriptional activator ELK1. Inhibits the FZR1- and probably CDC20-mediated activation of the anaphase promoting complex APC thereby regulating progression through the cell cycle. Regulates TCF7L2-mediated gene transcription and may play a role in epithelial-mesenchymal transdifferentiation.
Synonyms: MAD2B; REV7; POLZ2; FANCV
Tractability: Small molecule: a structure with a bound ligand is known. PROTAC: ubiquitination databases record sites on it; its protein half-life has been measured.
Gene: Protein-coding gene on chromosome 1 (11,657,230 to 11,692,605, reverse strand). Ensembl gene ENSG00000116670.
Subcellular location: Nucleus; Cytoplasm, cytoskeleton, spindle; Cytoplasm; Chromosome
Subcellular location (Human Protein Atlas): Nucleoplasm
Pathways (Reactome):
DNA Repair: Translesion synthesis by POLI; Translesion synthesis by POLK; Translesion synthesis by REV1
Gene Ontology:
Molecular function: JUN kinase binding; protein binding; protein-macromolecule adaptor activity; RNA polymerase II-specific DNA-binding transcription factor binding; transcription corepressor activity
Biological process: actin filament organization; DNA damage response, signal transduction resulting in transcription; double-strand break repair; error-prone translesion synthesis; negative regulation of canonical Wnt signaling pathway; negative regulation of cell-cell adhesion mediated by cadherin; negative regulation of double-strand break repair via homologous recombination; negative regulation of epithelial to mesenchymal transition; negative regulation of protein catabolic process; negative regulation of transcription by RNA polymerase II; negative regulation of ubiquitin protein ligase activity; positive regulation of DNA-templated transcription; positive regulation of double-strand break repair via nonhomologous end joining; positive regulation of isotype switching; positive regulation of peptidyl-serine phosphorylation; regulation of cell growth; translesion synthesis; DNA repair; mitotic spindle assembly checkpoint signaling; somatic diversification of immunoglobulins involved in immune response; telomere maintenance in response to DNA damage; regulation of epithelial to mesenchymal transition
Cellular component: anaphase-promoting complex; cytoplasm; nucleoplasm; nucleus; site of DNA damage; spindle; zeta DNA polymerase complex; chromatin; chromosome; site of double-strand break
Genetic constraint (gnomAD): Loss-of-function variants: 17 observed, 31.62 expected, observed/expected ratio (o/e) 0.54, 90% interval 0.37 to 0.81. The upper end of that interval is the gene's LOEUF score, 0.81, which puts it in group 3 of 6, group 1 being the genes least tolerant of losing a copy. Missense variants: 213 observed, 286.78 expected, observed/expected ratio (o/e) 0.74, 90% interval 0.66 to 0.83. Synonymous variants: 101 observed, 115.07 expected, observed/expected ratio (o/e) 0.88, 90% interval 0.75 to 1.04.
Homologues: Orthologues: chimpanzee MAD2L2 (100% identical), dog MAD2L2 (99% identical), guinea pig MAD2L2 (99% identical), pig MAD2L2 (99% identical), mouse Mad2l2 (99% identical), rabbit MAD2L2 (99% identical), macaque MAD2L2 (94% identical), tropical clawed frog mad2l2 (93% identical), zebrafish mad2l2 (85% identical), rat Mad2l2 (60% identical), Drosophila melanogaster PolZ2 (29% identical). Paralogues in human: MAD2L1 (25% identical).
Diseases named in the same sentence as MAD2L2 in open-access papers:
MAD2L2 is named in the same sentence as 58 diseases in open-access papers, as found by Europe PMC text mining. Sharing a sentence is not in itself a finding about the gene and the disease. The quoted sentences say what the papers report.
ovarian carcinoma (14 papers, 2017 to 2025). A malignant neoplasm originating from the surface ovarian epithelium. "In a CARM1-dependent way, EZH2 inhibitors can increase MAD2L2 and make HR-proficient ovarian cancer more sensitive to PARPi." (PMID 40612876, 2025). "Overall, our findings establish MAD2L2 as a significant regulator of tumor progression in ovarian cancer and contribute novel insights for OVCA treatment strategies." (PMID 38167649, 2024). "High expression of REV7/MAD2L2 shows higher survival probabilities in pancreatic cancer, ovarian cancer, and breast cancer, whereas low expression of REV7/MAD2L2 exhibits an unfavorable outcome." (PMID 35955544, 2022). "These slides revealed that both ovarian follicular cells and ovarian cancer stem cells exhibited moderate levels of MAD2L2 protein antibodies (stained blue), contrasting with the brownish-yellow staining of normal ovarian cells, highlighting their cytoplasmic and membrane localization." (PMID 38167649, 2024). "In addition to 53BP1 deficiency, EZH2-meditated epigenetic silencing of MAD2L2 (REV7), a critical factor involved in the 53BP1-dependent NHEJ repair pathway results in resistance to PARPi in ovarian cancer." (PMID 36284291, 2022). "In another study on ovarian cancer, suppression of mad2l2 increases cisplatin sensitivity." (PMID 30914796, 2019). "Higher REV7/MAD2L2 expression was associated with higher survival probabilities in pancreatic cancer, ovarian cancer and breast cancer, while low levels of REV7/MAD2L2 exhibited an unfavourable outcome." (PMID 37190285, 2023). "Besides, in HR-proficient ovarian cancer, EZH2 inhibition could promote sensitivity to PARP inhibitors via upregulation of MAD2L2 in a CARM1-dependent manner." (PMID 36793373, 2023). "In ovarian cancer cell lines with high CARM1 expression, EZH2 levels are upregulated, allowing activation of homologous recombination repair by exerting transcriptional repression on nonhomologous recombination repair-related genes, such as MAD2L2 (mitotic arrest deficient 2 like 2, MAD2L2)." (PMID 36263120, 2022).
breast cancer (13 papers, 2015 to 2025). A primary or metastatic malignant neoplasm involving the breast. "Among breast cancer subtypes, the top eight mutational rates were MAD2L2/FANCV (37.5%), FANCI (32%), ATR (32%), FAAP20 (30%), FAAP100 (28%), SLX4 (27%), FANCT (27%), and BRIP1 (26%) in breast invasive carcinoma NOS." (PMID 39421870, 2024). "It has been documented that MAD2L2 is overexpressed in many human cancer types, including prostate cancer, melanoma, hepatocellular carcinoma, and breast cancer." (PMID 38017538, 2023). "For instance, MAD2L2 was overexpressed in glioma, epithelial ovarian cancer, and breast cancer, while inactivation of MAD2L2 sensitized nasopharyngeal carcinoma cells to DNA‐damaging agents." (PMID 29360267, 2018). "Breast cancers and breast cancer cell lines overexpress several mitotic regulators, including kinases that regulate the SAC such as Nek2, Mad1L1, Mad2L1, Mad2L2, BubR1, BubR1B, Bub3, Cdc20, and Mps1/TTK." (PMID 29100415, 2017).
colorectal cancer (11 papers, 2017 to 2024). A primary or metastatic malignant neoplasm that affects the colon or rectum. "Mitotic Arrest Deficient 2 Like 2 (MAD2L2), a chromatin-binding protein and a component of DNA polymerase ζ, has been previously identified as an inhibitor of tumor growth in colorectal cancer." (PMID 38167649, 2024). "It has been shown that transfection of BTF3 siRNA into HCT116 cells reduces cell viability, induces apoptosis, blocks the cell cycle, and attenuates tumorigenicity of colorectal cancer cells by decreasing the activities of MAD2L2, MCM3, and PLK147." (PMID 38203709, 2023). "MAD2L2 inhibits the growth of colorectal cancer by degrading nuclear receptor coactivator 3; it is a poor prognostic factor for colon cancer." (PMID 36012568, 2022). "In conclusion, BTF3 is positively related to CRC and BTF3-siRNA attenuated the tumorigenicity of colorectal cancer cells via MAD2L2, MCM3 and PLK1 activity reduction." (PMID 31263147, 2019). "Taken together, according to our microarray findings, BTF3 seems to be association with MAD2L2, MCM3, and PLK1 through regulatory effects in different stages of mitosis, which affect proliferation and cell cycle of colorectal cancer cells." (PMID 31263147, 2019). "MAD2L2 is involved in mitosis checkpoint control; its expression is upregulated in colon cancer tissue as compared with the adjacent normal tissue, and there is excessive MAD2L2 expression in patients with colorectal cancer with poor prognosis." (PMID 28968959, 2017).
glioma (8 papers, 2017 to 2024). A benign or malignant brain and spinal cord tumor that arises from glial cells (astrocytes, oligodendrocytes, ependymal cells). "Cell-based experiments validated that the overexpression of c-MYC rescued the inhibition of cell proliferation, migration, and invasion caused by MAD2L2 silencing in glioma cells, and vice versa." (PMID 38017538, 2023). "In our study, we identified high expression of MAD2L2 in glioma samples, which was associated with tumor grade and prognosis." (PMID 38017538, 2023). "Furthermore, the baseline clinical information table revealed correlations between high MAD2L2 expression and glioma grade, IDH mutation status, and 1P19q co-deletion status." (PMID 38017538, 2023). "Within subtypes of brain cancer, the top three mutation rates were MAD2L2/FANCV (21.49%) in meningioma, XRCC2/FANCU (17%) in rhabdoid tumors, and ATM (16%) in pediatric high-grade gliomas." (PMID 39421870, 2024). "We found that MAD2L2 expression was highest in proliferative-like glioma stem cells, followed by glioma stem cells and differentiated glioma cells." (PMID 38017538, 2023). "The knockdown effect score of MAD2L2, representing gene necessity for cell survival, consistently scored below 0 across various tissue-originated cancer cell lines, including glioma cell lines." (PMID 38017538, 2023). "Upon further sub-division of the glioma cell population, we discovered that MAD2L2 expression was highest in proliferative-like glioma stem cells, followed by glioma stem cells and differentiated glioma cells." (PMID 38017538, 2023). "To investigate the potential role of c-MYC in mediating the function of MAD2L2 in glioma cells, we performed additional experiments." (PMID 38017538, 2023). "Bioinformatics analysis was performed based on data from public databases to explore the expression profile of Mitotic arrest deficient 2 like 2 (MAD2L2) and its potential function in glioma." (PMID 38017538, 2023). "To investigate the role of MAD2L2 in glioma progression, we examined the mRNA and protein expression levels of MAD2L2 in various glioma cell lines and two human astrocyte cell lines." (PMID 38017538, 2023). "Through in vitro and in vivo experiments, we confirmed that MAD2L2 promotes the maintenance of stemness and malignant behaviors in glioma, and the oncogene c-MYC plays a crucial role in these processes." (PMID 38017538, 2023). "To confirm how MAD2L2 affects glioma proliferation and stemness, we performed differential analysis and GSEA enrichment analysis on GBM samples from three cohorts: TCGA-GBM, CGGA325, and CGGA693." (PMID 38017538, 2023). "In this study, we report that MAD2L2 was upregulated in glioma and that high MAD2L2 expression promotes glioma proliferation, invasion, and maintenance of its stemness by regulating the oncogene c-MYC." (PMID 38017538, 2023). "GSEA enrichment analysis indicated a positive correlation between MAD2L2 and the activation of glioma stem cell pathways." (PMID 38017538, 2023). "The “Matrigel Transwell” invasion assay also revealed that ectopic MAD2L2 expression promoted glioma cell invasion." (PMID 38017538, 2023). "The Cancersea database demonstrated that in glioma, MAD2L2 was predominantly positively correlated with cell cycle, stemness, and proliferation scores." (PMID 38017538, 2023). "In our analysis, we utilized glioma single-cell data from 15 project sources in the TISCH database to demonstrate that MAD2L2 exhibited predominant expression in cancer cells." (PMID 38017538, 2023). "In the context of glioma, the Cancersea database revealed that MAD2L2 was primarily positively correlated with cell cycle progression, stemness features, and proliferation." (PMID 38017538, 2023). "This suggests that MAD2L2 plays a critical role in the survival and proliferation of numerous cancer cells, including glioma cell lines, making it a potential oncogene." (PMID 38017538, 2023).
glioma (continued). "To further investigate the impact of MAD2L2 on the clinical prognosis of glioma patients, we divided the patients into two groups based on the median value of MAD2L2 expression levels: high expression and low expression." (PMID 38017538, 2023). "Considering that glioma grade is a significant prognostic factor, we further explored the expression of MAD2L2 across different WHO grades (II-IV)." (PMID 38017538, 2023). "In this study, we conducted comprehensive bioinformatics analyses to investigate the role of MAD2L2 in glioma by accessing various databases." (PMID 38017538, 2023). "In summary, our results demonstrate elevated transcriptional and translational levels of MAD2L2 in cancer, particularly in glioma." (PMID 38017538, 2023). "To explore the potential mechanisms by which MAD2L2 affects glioma growth, we performed analysis on single-cell data from databases such as TISCH." (PMID 38017538, 2023). "We found that knockdown/overexpression of MAD2L2 inhibited/promoted glioma proliferation, migration, and invasion." (PMID 38017538, 2023). "In this study, we employed bioinformatics analysis to identify the upregulation of MAD2L2 in glioma and its correlation with tumor grade and prognosis, which was further validated by immunohistochemistry on patient samples." (PMID 38017538, 2023). "In conclusion, our findings suggest that MAD2L2 silencing inhibits the proliferation, migration, and invasion of glioma cells." (PMID 38017538, 2023). "Moreover, MAD2L2 was reported to be overexpressed in multiple cancers, such as glioma, breast cancer, and epithelial OVCA8,9." (PMID 38167649, 2024). "Finally, we calculated the tumor mutation burden (TMB) and found that the expression of MAD2L2 was highly associated with OVCA patients’ TMB, and the highest correlation ratio with MAD2L2 level was found in the low-grade glioma." (PMID 38167649, 2024). "Additionally, both wound healing assay and “Transwell” migration assay demonstrated that ectopic expression of MAD2L2 augmented the migratory ability of glioma cells." (PMID 38017538, 2023). "Taking these pieces of information together, we tentatively suggest that MAD2L2 may play a role in the proliferation and maintenance of the stemness state in glioma cells." (PMID 38017538, 2023). "Furthermore, we observed that the expression levels of MAD2L2 increased with the grade of glioma samples." (PMID 38017538, 2023). "Next, we explored the impact of MAD2L2 on the clinical prognosis of glioma patients." (PMID 38017538, 2023). "Additionally, the nomogram constructed based on MAD2L2 expression level could effectively predict the glioma patients’ 1-, 3-, and 5-year survival." (PMID 38017538, 2023). "Furthermore, we confirmed the effect of MAD2L2 on glioma by in vitro and in vivo experiments." (PMID 38017538, 2023). "The underlying mechanisms of MAD2L2 dysregulation in glioma have not been reported." (PMID 38017538, 2023). "However, the role and mechanism of MAD2L2 in glioma remains unclear to date." (PMID 38017538, 2023). "Therefore, the E2F-1/MAD2L2/c-MYC axis facilitates the stemness and aggressive behaviors, such as proliferation and invasion, in glioma, providing new insights for the treatment of this disease." (PMID 38017538, 2023). "The evidence suggests that c-MYC mediates the tumor-promoting effects of the MAD2L2, and MAD2L2/ c-MYC may serve as a potential therapeutic target for glioma treatment." (PMID 38017538, 2023). "Analysis of multiple glioblastoma-related datasets from GEO demonstrated a positive correlation between MAD2L2 expression and the MYC pathway, indicating that MAD2L2 may influence glioma growth and stemness by affecting c-MYC activity." (PMID 38017538, 2023). "Moreover, GSE124145 revealed higher expression of MAD2L2 in glioma stem cells compared to non-stem cells." (PMID 38017538, 2023). "However, the role of MAD2L2 in glioma stemness has not been reported yet." (PMID 38017538, 2023).
colon cancer (7 papers, 2017 to 2023). "Furthermore, ZKSCAN3 upregulation suppressed the expression of the mitotic spindle checkpoint protein, Mitotic Arrest Deficient 2 Like 2 (MAD2L2) by inhibiting its promoter activity and eventually inducing chromosomal instability in colon cancer cells." (PMID 36012568, 2022). "In conclusion, ZKSCAN3 could be responsible for WNT/β-catenin-induced chromosomal instability in colon cancer cells through the suppression of MAD2L2 expression." (PMID 36012568, 2022). "A proximity ligation assay (PLA) was used to investigate interactions between REV3L, REV1, and MAD2L2 in normal (CCD-18Co) and colon cancer cells." (PMID 29435169, 2018). "However, the number of interactions between REV3L and REV1, REV3L and MAD2L2, and REV1 and MAD2L2 were reduced to 44/cell, 27/cell, and 26/cell, respectively, in HCT-116 colon cancer cells and to 19.2/cell, 59/cell, the 51/cell in DLD-1 colon cancer cells." (PMID 29435169, 2018). "MAD2L2 interacted with NCOA3 and suppressed proliferation and migration of colon cancer cells." (PMID 30613364, 2018).
Fanconi anemia (7 papers, 2020 to 2025). Fanconi anemia (FA) is a hereditary DNA repair disorder characterized by progressive pancytopenia with bone marrow failure, variable congenital malformations and predisposition to develop hematological or solid tumors. "In line with the emerging view of the role of Fanconi Anemia proteins in fork protection, it is possible that compromised fork stabilization pathways, in part, contribute to tumor initiation and progression in patients harboring pathogenic mutations in MAD2L2." (PMID 36075897, 2022). "Moreover, biallelic mutations in MAD2L2 have been found in patients with Fanconi Anemia, which are characterized by increased genome instability and predisposition to congenital abnormalities, bone marrow failure, and cancer." (PMID 36075897, 2022). "By doing so MAD2L2 affects the development and treatment of human disease, such as Fanconi Anemia and cancer, in which it determines the sensitivity of BRCA1-deficient cancers to treatment with Parp inhibitors." (PMID 34521823, 2021).